CAV1 (caveolin 1)
Diseases named in the same sentence as CAV1 in open-access papers (continued):
Sharing a sentence is not in itself a finding about the gene and the disease.
tumor (continued). "We sought to define key regulatory genes that may modulate both p27 and caveolin-1 expression in basal-like tumor cells, and one such candidate is the peroxisome proliferator-activated receptor (PPAR)-γ." (PMID 17764562, 2007). "However, although there is evidence that this pathway plays a role in tumour suppressor activity caveolin-1 also has other effects on the cell cycle." (PMID 18949068, 2007). "Therefore it is likely that multiple functions contribute to the role of caveolin-1 as a tumour suppressor gene." (PMID 18949068, 2007). "In face of this controversy one has to assume that the role of Caveolin-1 as both tumour suppressor and promoter might be context-depending." (PMID 17915016, 2007). "Reduced CAV1 mRNA level was significantly associated with increasing tumour size (P=0.041), and negative oestrogen receptor status (P=0.021)." (PMID 15305200, 2004). "Such a subcellular location as opposed to its more traditional position at the plasma membrane appears to be a prevailing feature within different types of human cancer where caveolin-1 levels are elevated as is the case for tumours of the colon, pancreas and prostate." (PMID 14612902, 2003). "Additionally, the expression of recombinant caveolin-1 is sufficient to restrict the growth potential of transformed cells isolated from primary tumours of the breast, lung and ovaries." (PMID 14612902, 2003). "The aim of the study is to determine if caveolin-1 expression might have value as a prognostic marker and if it has a potential role in tumour progression." (PMID 14612902, 2003). "In this regard, caveolin-1 is proposed to represent a novel tumour suppressor protein." (PMID 14612902, 2003). "According to our criteria, 32 out of 79 (40.5%) tumours were positive for caveolin-1." (PMID 12402154, 2002). "For patients with a tumour overexpressing caveolin-1, closer follow-up should be performed to find recurrence, and adjuvant therapy may be beneficial." (PMID 12402154, 2002). "Moreover, caveolin-1 immunopositivity is positively correlated with tumour diameter and histopathologic grade in this cancer as well." (PMID 12402154, 2002). "Under some conditions, caveolin-1 has been shown to suppress growth of specific cell lines in vitro and in vivo, and some have suggested that caveolin-1 functions as a tumour suppressor gene." (PMID 12402154, 2002). "Conversely, Cav1 can promote cancer progression and metastasis depending on the cellular context by enhancing cell survival under stress, facilitating metastasis and invasion, modulating the tumor microenvironment, and activating pro-oncogenic signaling pathways." (PMID 40963741, 2025). "Notably, CAV1 was highly enriched in tumor cells, and its expression may significantly influence the cell type-specific predisposition to the ferroptosis phenotype." (PMID 40180904, 2025). "While CAV1 has been shown to regulate the organization of isotype-specific B-cell antigen receptors and in turn B-cell tolerance, IHC analysis in the study cohort showed that CAV1 is implicated in TB via the expression on tumor cells, not on immune cells." (PMID 40082664, 2025). "Alterations in FOS expression have been associated with malignant phenotypic changes in tumor cells, while downregulation of CCL2 and CAV1 may influence immune cell recruitment and signaling within the tumor microenvironment, thereby affecting tumor immune evasion and progression." (PMID 41155558, 2025). "The downregulation of CAV1 may result in increased tumor growth and progression." (PMID 40898538, 2025). "Additionally, CAV1 could impact the metabolic demands of tumor cells by influencing the uptake and metabolism of fatty acids." (PMID 40180904, 2025). "Furthermore, CAV1 can negatively regulate transforming growth factor β (TGFβ) signaling, and TGFβ signaling activation is crucial for inducing mitochondrial autophagy in tumor matrix cells." (PMID 39763653, 2024).
tumor (continued). "However, it remains unclear how Cav-1 is involved in the response to matrix structural remodeling of the ECM during tumor progression." (PMID 39318372, 2024). "Importantly, Cav-1 deficiency did not significantly affect primary tumor growth in vivo but markedly decreased lung metastasis in mice bearing Cav-1 KO 4T1 cells compared to WT 4T1 cells." (PMID 39244591, 2024). "Hence, CAV1’s prognostic impact could be context-dependent, considering not only tumor biology and receptor status, but also the stage of disease presentation (early versus advanced stages)." (PMID 39596307, 2024). "In addition, in metastasis-associated macrophages, the deletion of Cav-1 can enhance VEGF-A/VEGFR1 activity, induce the downstream expression of MMP-9 and colony-stimulating factor-1 (CSF-1), and jointly promote angiogenesis and tumor metastatic growth." (PMID 37828916, 2023). "Through exosomes, tumor cells can be helped to mediate intercellular communication in specific microenvironmental pH conditions, thus promoting the exchange of specific molecules such as Cav-1, which lead to the phenotypic changes of recipient cells and enhance tumorigenicity." (PMID 37056561, 2023). "Notably, this tumor-suppressive role relies on the phosphorylation of serine-80 in caveolin-1." (PMID 38067108, 2023). "However, in colon cancer, the re-expression of CAV1 blocked tumor formation." (PMID 37919422, 2023). "Besides its effects on the immune components of the tumor stroma, the molecular interplay between Cav1 and cell metabolism has been established, with its high expression suppressing c-Myc-induced metabolic reprogramming with an impact on breast stem cancer cells." (PMID 36430209, 2022). "Thus, targeting epithelial CAV1, particularly inhibiting the gain in advanced PCa, maybe the better therapeutic strategy for eliminating cancer cells because tumor starvation may additionally be induced." (PMID 35155239, 2022). "Hence, from a tumor perspective, the increased activity of CAV1 must be considered oncogenic." (PMID 35158857, 2022). "Since bulk RNA sequencing of HNSCC tissue provides the average gene expression of both tumor cells and stromal cells, our result may mainly reflect the influence of stromal CAV1 expression on the radiosensitivity of HNSCC, and methodologies with higher resolution may better elucidate our findings." (PMID 35505641, 2022). "Additionally, CAV1 appears necessary for mitochondrial functionality in normal cells, but, in cancer cells, mitochondrial CAV1 enhances cell survival in response to stress and inhibits mitochondrial respiration increasing tumor malignancy." (PMID 35740528, 2022). "However, whether CAV-1 functions as an oncogene or a tumor suppressor during cancer progression is still controversial." (PMID 33935779, 2021). "Among the miRNA with reduced expression in SMZL, nine can target CAV1, including miR-199a, miR-376, and miR-485, and may promote tumor progression by inducing the overactivation of transcriptional factors (IGF1R for miR-376a; IKKβ and NFκB pathway for miR-199a)." (PMID 34590593, 2021). "However, CAV1 overexpression has been reported in malignant EC of different types of solid tumors; tumor cells could increase CAV1 expression as a mechanism for evasion of apoptosis and RR." (PMID 34900673, 2021). "Finally, we found a within-patient difference metric between caveolin-1 and Sox-2 — calculated as the difference between the percentage of positivity of caveolin-1 and Sox-2 in a patient’s tumor sample — to be a strong predictive metric of cetuximab response in these patients with HNSCC." (PMID 34546978, 2021). "However, this trend could not be seen consistently, which is in line with the ambiguous role of Cav-1 in tumor progression described in literature." (PMID 33774714, 2021).
tumor (continued). "In-line with previous studies, the statistically significantly higher expression of Cav-1 in the benign stroma versus tumor stroma demonstrates that Cav-1 may play an important role in carcinogenesis and further studies may provide insight into the evolutionary biology of OvCa." (PMID 34813586, 2021). "However, the total Cav-1 expression was examined in relation to the tumor stages." (PMID 33774714, 2021). "However, whether CAV1 act as an oncogene or a tumor suppressor gene in cancer progression is still unclear." (PMID 33712015, 2021). "Therefore, we hypothesized that CAV1 could facilitate tumor development and GEM-resistance via immune escape mechanism." (PMID 35127724, 2021). "However, Cav-1 regulates glucose metabolism in tumor cells mainly by regulating glucose transporter 3 (GLUT3/SLC2A3) uptake of glucose, which leads to increased aerobic glycolysis and increases intracellular ATP production, thus maintaining the growth and survival of tumor cells." (PMID 34955837, 2021). "It was also reported that reduced editing of COPA was implicated in the pathogenesis of HCC and editing of COPAWT may switch it from a tumor-promoting gene to a tumor suppressor by deactivating the PI3K/AKT/mTOR pathway through downregulation of caveolin-1 (CAV1)." (PMID 33824874, 2021). "Early in tumorigenesis CAV1 levels may decline and allow tumor cells to multiply." (PMID 33868995, 2021). "Importantly, however, CAV1 also functions as a tumor suppressor by aiding E-cadherin in the sequestration of β-catenin, thereby impeding activation of the β-catenin/Tcf-Lef-dependent transcription of genes, like survivin, cyclooxygenase-2, cyclin D1, and many others that favor cancer development." (PMID 32458269, 2020). "However, in recent years, some studies have reported that Cav-1 could exert an anti-apoptotic potential, enhances the tumor cell migration and invasion, and improves the chemoresistance." (PMID 32117718, 2020). "Thus, CAV1 participates both as a tumor suppressor and promoter in cancer." (PMID 32458269, 2020). "Lowering CAV1 levels in tumor EC may thus be suited to improve the outcome of RT in cancer." (PMID 32273493, 2020). "Such discrepancy might be explained by the variations of Cav1 expression during disease progression, in that the balance between caveolae signaling and mechanical functions in response to the extracellular environment changes during tumor mass growth." (PMID 32532976, 2020). "Moreover, in clinicopathological characteristics of patients, a high CAV1 expression directly correlates with higher levels of serum tumor antigens, with the rate of advanced tumor stage, and with significantly worse outcomes in both overall and disease-free survival." (PMID 32849491, 2020). "Caveolin-1 expression is hypothesized to increase as cancer advances to promote tumor progression." (PMID 32676485, 2020). "Then, we asked whether CAV1 expression in ex-tumor cells affected IRE1α dependent signaling." (PMID 32811828, 2020). "The percentage of black tumor mass found, indicated that the expression of CAV1 increased metastasis roughly threefold in comparison to cells that do not express CAV1 (Mock cells: 13% of lung mass) and the expression of E-cadherin decreased the tumor mass to a similar extent." (PMID 32152405, 2020). "Moreover, it has been shown that MS leads to increased caveolin-1 expression at tumor sites, again suggesting that elevated transcellular endocytosis processes could be leading to selective tumor BBB permeability within the tumors." (PMID 33198244, 2020). "Altogether, these results indicate that Cav-1 may modulate c-Myc and its downstream metabolism-related proteins, and therefore plays a critical role in modulating aerobic-glycolysis activity during breast carcinogenesis." (PMID 32528105, 2020). "Therefore, molecules such as Cav-1 or SPARC could be tumour-penetrative biomarkers, as well as prognostic biomarkers, for nab-PTX." (PMID 32532230, 2020).
tumor (continued). "However, our study indicated CAV1 served as a tumor suppressor in GC." (PMID 32386516, 2020). "Moreover, the direct contact between EC and tumor cells seemed to be important, because cultivation of PCa cells with conditioned medium collected from CAV1-proficient or -deficient EC was not sufficient to induce cell death." (PMID 32273493, 2020). "However, the possible role of the ER in the tumor suppressor activity of CAV1 is completely unknown." (PMID 32811828, 2020). "Thus, the interaction between Cav-1 and cadherin may greatly influence cell adhesion and tumor cell metastasis." (PMID 31759347, 2019). "Besides, Cav-1 is essential for miR-203-dependent tumor cells invasion and migration inhabitation." (PMID 31759347, 2019). "Furthermore, the in vivo data demonstrated that TDE-containing Cav-1 (Exo-Vc) could significantly increase the tumor incidence of Du145 shCav1 cells compared with phosphate-buffered saline (PBS) or TDE purified from Du145 shCav1 (Exo-shCav1)." (PMID 31685812, 2019). "Although Y14 phosphorylation of Cav1 was associated with inhibition of cell proliferation and tumor growth, the capacity for invasion, assessed here based on expression of Cav1 WT relative to non-phosphorylatable Cav1Y14F and of the Cav1Y14D phosphomimetic, was retained." (PMID 31803361, 2019). "It is unclear whether Cav-1 inhibits or promotes tumor growth and progression." (PMID 31297035, 2019). "A coculture system, by which a loss of stromal fibroblast CAV1 induces a “lethal tumor microenvironment,” demonstrated that MCF7 epithelial cancer cells induce oxidative stress in adjacent CAFs, resulting in the autophagic/lysosomal degradation of stromal CAV1." (PMID 31014370, 2019). "Besides, Cav-1 also modulates autophagy of tumor cells, significantly impacting cancer progression." (PMID 31759347, 2019). "Cav1 might play an important physiological role in the defence against tumour‐derived exosomes via the degradation of Fzd2, thereby suppressing Wnt5a‐driven malignant transformation or inhibition of tumour‐derived exosomes internalization through an unidentified mechanism." (PMID 29502342, 2018). "We, however, could not show any association of CAV1 overexpression with either Gleason grade or pathological tumour stage." (PMID 29402961, 2018). "Neither CAV1 nor ITGB1 expression associated with Gleason score or pathological tumour stage (pT)." (PMID 29402961, 2018). "Although the loss of Cav1 is not sufficient to causally drive cell transformation, it is a critical step in the acquisition of the oncogene‐induced transformed phenotypes in both tumour cells and normal cells surrounding the tumour." (PMID 29502342, 2018). "However, in the in vivo environment, stable knockdown of PTBP3 may inhibit tumour differentiation and growth by affecting the tumour microenvironment and not only through the CAV1 pathway." (PMID 29752441, 2018). "Finally, it could be added that CAV1, besides being a tumor suppressor, can also act as an inflammation suppressor that can be considered in the studies on CAV1-null tumors." (PMID 30246033, 2018). "Therefore, we sought to investigate whether CAV1 depletion might result in an increased uptake of trastuzumab in tumor xenografts and human tumor samples." (PMID 30510281, 2018). "This hypothesis may further explain the role of Cav-1 as a tumor suppressor." (PMID 28546853, 2017). "Since cav-1 loss results in increased expression of these proteins in murine mammary glands, it’s likely that this aberrant ECM may contribute to a situation which favors the early events leading to tumor initiation." (PMID 28187162, 2017). "Thus, normal Cav1-positive stroma might inhibit tumor progression and improve the efficiency of radiation therapy, whereas a Cav1-dependend transformed and more reactive tumor stroma fosters tumor growth and contributes to therapy resistance." (PMID 28112237, 2017). "Interestingly, Cav-1 also acts as an oncoprotein depending on the tumor type and/or tumor stage." (PMID 28546853, 2017).
tumor (continued). "However, the upregulation of Cav-1 in human cancer cells may serve as a tumor promoter role in the majority of human cancer types." (PMID 28828003, 2017). "Furthermore, patients with advanced PCa had also increased serum levels of Cav1 suggesting a secretion of Cav1 from PCa cells that may contribute to the tumor-promoting effects of Cav118." (PMID 28112237, 2017). "Notably, caveolin-1 has different functions in variety of cancers and may act both as a tumor suppressor and as a tumor-promoting gene." (PMID 29221140, 2017). "Consequently lowering Cav1 levels specifically in tumor epithelial cells may be suited to increase the efficiency of IR in PCa." (PMID 28112237, 2017). "Cav1 may therefore constitute a valuable therapeutic target to overcome therapy resistance by sensitizing both, radioresistant tumor cells and the radioresistant tumor vasculature, to the cytotoxic effects of IR19." (PMID 28112237, 2017). "Therefore we concluded that Cav1 might be a promising therapeutic target for combinatorial therapies to counteract radiation resistance of PCa at the level of the tumor vasculature." (PMID 28112237, 2017). "This biphasic pattern may support the different roles of Cav-1 as a tissue and stage-specific tumor modulator, where it acts as an inhibitor or promoter of tumor formation and progression depending on its protein interaction partners such as growth factor receptors or cell adhesion molecules." (PMID 28828003, 2017). "However it was also reported that stromal Cav-1 favors tumor invasion and metastasis." (PMID 29141593, 2017). "In conclusion, the function of CAV1 as a tumor suppressor is not altered by CAV1 mutations in Y14." (PMID 27259249, 2016). "Further, reintroduction of CAV1 enhanced Ca2+ uptake into mitochondria, suppressed cell growth, colony formation, and induced apoptosis, implying that high CAV1 level may suppress mitochondrial function as a mechanism to mediate a suppressor activity in H-Ras-driven tumours." (PMID 27852311, 2016). "Importantly, CAV1 function as a tumor suppressor in tumor formation assays was not altered by the Y14F mutation." (PMID 27259249, 2016). "To rule out the possibility that mutations of Y14 may have inhibited CAV1 function in a non-specific manner, we determined whether they altered a different feature of CAV1, namely its tumor suppressor function." (PMID 27259249, 2016). "Furthermore, our results demonstrated that the expression of caveolin-1 can improve T-DM1 internalization and drug efficacy, although tumor stage and the expression of molecular effectors may affect the role of caveolin-1 during tumor progression." (PMID 26172389, 2015). "Other studies have shown that Cav-1 may have a tumour suppressive role." (PMID 25756273, 2015). "Thus, the role CAV1 plays in tumor development and progression appears to be context dependent." (PMID 26054531, 2015). "Goetz and colleagues, reported that Cav1 expression in fibroblasts remodeled the extracellular matrix to regulate cell shape and to stimulate migration and invasion of cancer cells in vitro, and promote tumor growth and metastasis in vivo in a p190RhoGAP dependent manner." (PMID 26179155, 2015). "Together, higher Cav-1 expression is correlated with worse outcomes, is essential for tumor growth and invasion (both in vitro and in vivo), is responsible for promoting resistance to therapies, and may serve as a prognostic/predictive biomarker and target in PC." (PMID 26065715, 2015). "Thus based on these previous results an immunohistochemistry analysis was performed on sections of the tumor to evaluate the expression of cav-1 and Acsvl3, NSCLC biomarkers whom overexpression is correlated with tumor growth, invasiveness and metastatic potential." (PMID 25015569, 2014). "Furthermore, CAV1 is known to block MAPK signaling as part of its tumor suppressive activities." (PMID 25313138, 2014).